SIRT1 (sirtuin 1)
Diseases named in the same sentence as SIRT1 in open-access papers (continued):
Sharing a sentence is not in itself a finding about the gene and the disease.
Infertility (28 papers, 2016 to 2025). "Research based on the Sirt1−/− mouse model indicated that SIRT1-deficient male mice have relatively smaller testes and suffer from infertility due to poor spermatogenesis and abnormal sperm maturation." (PMID 39201341, 2024). "This pioneering study, therefore, aims to identify the role of MetF on oxidative stress with existing SIRT1 Polymorphism in infertile cases where SIRT1 polymorphism is associated with aging and OS." (PMID 30555352, 2018). "SIRT1 is notable for its capability to promote antioxidant defenses, so its absence exacerbates the oxidative damage caused by varicocele, which then amplifies the resulting damage to DNA and ultimately leads to infertility." (PMID 40422880, 2025). "Depletion of SIRT1 results in impaired mitochondrial function accompanied by elevated levels of ROS, increased lipid peroxidation, and DNA harm in both male and female reproductive cells (sperm and eggs), ultimately causing infertility." (PMID 40524181, 2025). "Deficiency of silent information regulator 1 (SIRT1) can trigger inflammation, mitochondrial malfunctioning, and apoptosis through the hypothalamic-pituitary-ovarian axis, producing poor quality oocytes, leading to infertility." (PMID 37428803, 2023). "Deficiency of VD is associated with a decrease in SIRT1 and other antioxidants, which may deter natural reproductive functions leading to infertility." (PMID 37428803, 2023). "The deficiency of VD is associated with a decrease in SIRT1 and other antioxidants, which may deter natural reproductive functions leading to infertility." (PMID 37428803, 2023). "However, no human study refers to the role of MetF during OS in presence of SIRT1 genetic polymorphism of infertile females." (PMID 30555352, 2018). "Patients with varicocele present an increase in oxidative stress, exhibiting higher than normal levels of ROS, which lead to infertility, as well as a reported SIRT1 deficit in some cases." (PMID 40422880, 2025). "SIRT1 also affects endometrial receptivity by downregulating FOXO1, contributing to infertility, so SIRT1 is a promising therapeutic target." (PMID 41278208, 2025). "In the blood sera, it was only possible to detect SIRT1 in the range of 0.04–24.50 ng/ml in 20% of all sera (5 out of 25 samples) derived from fertile men and in 30.7% of sera (27 out of 88 samples) of infertile men." (PMID 38913627, 2024). "Research has indicated that the inhibition or knockdown of SIRT1 can intensify oxidative stress and DNA damage, leading to mitochondrial dysfunction and ultimately culminating in ovarian ageing and infertility." (PMID 38581065, 2024). "The additional parameter examined in our study was SIRT1 in the seminal plasmas and blood sera of fertile and infertile men." (PMID 38913627, 2024). "A similar pattern is recorded in our sample, where SIRT1 was significantly lower in female participants living with infertility compared with fertile controls." (PMID 37428803, 2023). "Serum levels of MnSOD, SIRT1, visfatin, GR, VD, adrenaline, and cortisol were analyzed by ELISA and were compared in fertile and infertile samples using the Mann Whitney U test." (PMID 37428803, 2023). "Sirt1 knock out (KO) mice (Sirt1-/-) are affected by infertility in both sexes with oocytes and sperm failing to mature." (PMID 33573212, 2021). "Furthermore, reduced SIRT1 levels contribute to mitochondrial dysfunction by elevating ROS production, lipid peroxidation and DNA damage in oocytes, ultimately leading to infertility." (PMID 40062928, 2025). "This review aims to discuss the interaction between SIRT1 and telomeres and investigate whether SIRT1 and telomeres can serve as indicators of infertility and the efficacy of assisted reproduction techniques based on recent findings." (PMID 39201341, 2024). "Sirtuin 1 (SIRT1), a histone deacetylase, was found to be involved in regulating transcription, energy metabolism, and oxidative stress and to contribute to sperm abnormalities in infertile men." (PMID 34344298, 2021).
Infertility (continued). "We hypothesized that Metformin buffers the increased OS in presence of SIRT1 polymorphism by regulating the NAD biosynthesis and increasing the expression of SIRT1, thus improving the reproductive microenvironment in infertile females." (PMID 30555352, 2018). "Additionally, the current study’s findings demonstrated that SP, L-car, and their combination exhibited a significant expression of SIRT1, suggesting that SP and L-car may have a protective effect in the regeneration of ovarian tissues in our infertile rats." (PMID 40954150, 2025). "The study suggests that VD deficiency can result in decreased levels of antioxidants and SIRT1, leading to inflammation, mitochondrial malfunctioning, and apoptosis through the hypothalamic-pituitary-ovarian axis, resulting in poor-quality oocytes and infertility." (PMID 37428803, 2023). "Recently, it has been shown that SIRT1 and SIRT3 proteins are inversely correlated with oxidative stress biomarkers and sperm DNA fragmentation in infertile patients." (PMID 38255792, 2024). "However, we believe that SIRT1 may be a potential therapeutic target and should be widely investigated, especially since significant differences in the levels of this enzyme were demonstrated between fertile men and infertile male patients." (PMID 38913627, 2024).
Arthritis (27 papers, 2013 to 2026). Inflammation of a joint. "Our result further underlines the role of SIRT1 and macrophage metabolism in the development of arthritis." (PMID 35821263, 2022). "Further, collagen-induced arthritis is attenuated in SIRT1-transgenic mice associated with an increase level of M2 macrophage markers." (PMID 34639026, 2021). "The deficiency of SIRT1 in endothelial cells delayed the resolution of experimental arthritis." (PMID 34887866, 2021). "It is important to note that the significance of the SIRT1 results were largely driven by a single aged animal (M791), that was euthanized due to severe arthritis – a disease of eugeric aging." (PMID 38577492, 2024). "Some studies hold that SIRT1 can expedite the deterioration and degradation of collagen II in arthritis mice." (PMID 35109750, 2022). "Deletion of SIRT1 was found to suppress collagen-induced arthritis but aggravate serum transfer arthritis." (PMID 29459717, 2018). "On day 38, the mean clinical arthritis score of SIRT1 Tg-CIA mice (2.6 ± 0.4) was significantly lower than that of WT CIA mice (6.6 ± 0.68)." (PMID 28966618, 2017). "Down-regulation of SIRT1 expression by lentiviral shRNA significantly decreased the arthritis index score and alleviated joint cartilage of CIA rats." (PMID 29179491, 2017). "To ascertain the role of the myeloid cell-specific SIRT1 deletion in inflammatory arthritis, we generated mSIRT1 KO mice and induced passive K/BxN arthritis in mSIRT1 KO mice and matched littermate control (WT) mice." (PMID 24498364, 2014). "Our results provide in vivo evidence that myeloid cell-specific deletion of SIRT1 exacerbates inflammation and bone erosion in K/BxN serum transfer arthritis." (PMID 24498364, 2014). "Moreover, myeloid deletion of SIRT1 inhibited dendritic cell maturation and further alleviated arthritis in collagen-induced arthritis (CIA) mice." (PMID 29179491, 2017). "In addition, increased SIRT1 activity has been reported to alleviate arthritis by suppressing VEGF and inhibiting synovial angiogenesis." (PMID 28966618, 2017). "Thus, to investigate the in vivo function of SIRT1 in RA, we generated mSIRT1 KO mice and explored the specific contribution of myeloid cell-derived SIRT1 using the K/BxN serum transfer arthritis model." (PMID 24498364, 2014). "Moreover, the role of SIRT1 in arthritis models is controversial." (PMID 29459717, 2018). "Interestingly, other proinflammatory cytokines participating in arthritis, including IL-6, have been reported to activate cathepsin B and therefore could also trigger the cleavage of Sirt1." (PMID 23844973, 2013). "Resveratrol alleviated arthritis through the activation of Nrf2-ARE (antioxidant response elements) signaling pathway via SIRT1/NF-κB/miR-29a-3p/Keap1 and SIRT1/NF-κB/miR-23a-3p/cul3 signaling pathway." (PMID 33499333, 2021). "As a cytokine that mediates joint inflammation in arthritis, tumor necrosis factor α (TNF-α) was also found able to decrease SIRT1 activity and induce its cathepsin B-mediated cleavage and result in cartilage-specific gene expression inhibition in TNF-α-treated cells." (PMID 27863529, 2016). "Therefore, activating SIRT1 and inhibiting NF-KB/MAPK also play an important role in arthritis." (PMID 35109750, 2022).
chronic kidney disease (27 papers, 2014 to 2025). Impairment of the renal function secondary to chronic kidney damage persisting for three or more months. "Sirtuin 1 (SIRT1) is implicated in oxidative stress, inflammation, and fibrosis—processes central to chronic kidney disease (CKD) and cardiovascular complications." (PMID 41009597, 2025). "The malfunctioning AMPK/SIRT1/PGC‐1α pathway worsens chronic kidney disease through three connected problems." (PMID 41268687, 2025). "Further, T4O inhibited ER stress-induced vascular calcification in chronic kidney disease mice by stimulating SIRT1-mediated inhibition of the PERK PERK-eIF2α-ATF4 pathway." (PMID 40109860, 2025). "Beyond cardiovascular health, the systemic effects of sKL, particularly its influence on the Sirt1 pathway, suggest broader applications in the treatment of age-related diseases such as chronic kidney disease and neurodegeneration." (PMID 40894259, 2025). "Aminophylline suppresses chronic renal failure progression by modulating the SIRT1/AMPK/mTOR-mediated autophagy process." (PMID 38808395, 2024). "Several clinical studies have suggested that AKI is an important risk factor for progressive chronic kidney disease (CKD), in which SIRT1 plays a pivotal role." (PMID 35277012, 2022). "Sirtuin-1 also plays a role in LVH, with sirtuin-1 alleles being risk factors for LVH in chronic kidney disease patients." (PMID 31434333, 2019). "This suggests that dysregulation of vascular SIRT1 and SIRT3 may contribute to an increased risk of atherothrombotic events in patients with chronic kidney disease, a predominant cause of mortality in this demographic." (PMID 41567643, 2025). "Sirt1 is a promising target for chronic kidney diseases, including DN." (PMID 29867511, 2018). "Therefore, SIRT1 can improve DN and protect the kidney from acute injury, thereby delaying senescence and improving the prognosis of chronic kidney disease." (PMID 25386563, 2014). "Chronic kidney disease (CKD) is characterized by progressive renal fibrosis, oxidative stress, and sustained inflammation, with disease progression primarily driven by dysfunction of the AMPK/SIRT1/PGC‐1α signaling axis." (PMID 41268687, 2025).
lupus (26 papers, 2013 to 2025). "The results suggested that the overexpression of SIRT1 in vivo was associated with lupus pathogenesis and that SIRT1 inhibition mitigated the damage induced by lupus in MRL/lpr mice." (PMID 34887866, 2021). "SIRT1-deficient mice show elevated T cell activation and a lupus-like autoimmune phenotype." (PMID 41159029, 2025). "In a publication by Wang and collaborators (2014), the authors point out that deficiency of SIRT1 is related to the development of autoimmune syndromes, such as lupus in mice, where high titers of antinuclear antibodies and deposition of immunoglobulin in the kidneys can be found." (PMID 29194364, 2017). "SIRT1 promoter rs3758391 was shown to modify the morbidity risk due to systemic lupus erythematosus (SLE), and the T allele acts as a risk factor for progression of nephritis and a higher SLE disease activity index." (PMID 37695462, 2024). "In the present study, we aimed to investigate the effect of PNS on reversing SR in lupus mice and determine whether PNS reverses P-gp-mediated SR via SIRT1/FoxO1/MDR1 signalling in lymphocytes of lupus mice, which may be the major mechanism underlying the SR reversal potential of PNS in lupus." (PMID 35022006, 2022). "In Consiglio’s research, the SIRT1 promoter variant rs3758391 was found to be connected with SLE incidence, and the rs3758391 T allele may be linked to higher SLEDAI and lupus nephritis scores." (PMID 38835801, 2024). "The activator of SIRT1 plays a protective role in pristane-induced lupus mice, with the alleviation of proteinuria and decreased deposition of immune globulin in the kidneys." (PMID 34887866, 2021). "In contrast, the activation of SIRT1 by resveratrol, a SIRT1 activator, attenuates proteinuria, glomerulonephritis, and the serum levels of IgG1 and IgG2a in mice with pristane-induced lupus." (PMID 34887866, 2021). "Highlighting pathological SIRT1 regulation in mature B cells, systemic lupus erythematosus patients display significantly low SIRT1 levels, and SIRT1 is negatively correlated with an increased frequency of CD19+ B cells in these patients." (PMID 34946805, 2021). "The overexpression of SIRT1 was found in CD4+ T cells of a murine lupus model, however, SIRT1-null mice showed with immunoglobulin deposition in the kidneys and a high level of serum antinuclear antibody." (PMID 34887866, 2021). "Knocking down Sirt-1 in lupus mice leads to a temporary enhancement of H3 and H4 acetylation, accompanied by attenuated lupus symptoms such as reduced serum levels of anti-dsDNA, IgG deposition in glomerular and histological changes." (PMID 31611879, 2019). "SIRT1 knockout (KO) mice develop eyelid inflammation in infancy, and a lupus-like nephritis at later ages." (PMID 24386389, 2013). "Studies on lupus CD4+ T cells have shown that UV-B radiation inhibits SIRT1-mRNA and protein expression by activating AhR and suppressing DNMT1 activity in CD4+ T cells by binding upstream of the SIRT1 promoter translation initiation site, thus mitigating the progression of the pathological process." (PMID 37483618, 2023). "The treatment of pristane-induced lupus mice with RES may inhibit CD4+ T cells by triggering the silent mating type information regulator 2 homolog 1 (SIRT1)." (PMID 37492083, 2023).
lupus (continued). "In Consiglio's study, SIRT1 promoter rs3758391 was implicated to modify SLE morbidity, while rs3758391 T allele may contribute to a higher systemic lupus erythematosus disease activity index (SLEDAI) and lupus nephritis." (PMID 33981300, 2021). "SIRT1 overexpression was found in CD4+ T cells of a murine lupus model, suggesting that upregulated SIRT1 may contribute to the SLE pathogenesis." (PMID 33981300, 2021). "Moreover, resveratrol (RSV), an activator of SIRT1, has been shown to be protective against pristane-induced lupus mice, when alleviation of proteinuria and decreased deposition of immune globulin in the kidneys were observed." (PMID 33981300, 2021). "Indeed, activation of Sirt1 by resveratrol has been shown to lead to a reduced production of IgG1 and IgG2a in pristane-induced lupus mice as well as antigen-specific IgE in OVA-immunized mice." (PMID 26697020, 2015). "However, suppression of SIRT1 in an established mouse model of lupus (MRL/lrp mice) decreases autoantibody production and renal pathology." (PMID 24386389, 2013). "PNS inhibited SIRT1/FOXO1/MDR1 signaling pathway in lymphocytes and reversed P-gp-mediated steroid resistance in lupus." (PMID 37483618, 2023). "In a RES-treated atherosclerosis-prone lupus mouse model, RES tends to increase mRNA levels of sirtuin 1, and decrease vascular endothelial growth factor and CX3CL1 (neurotactin ligand) mRNA in the hippocampus." (PMID 37492083, 2023). "GpS can regulate autophagy and mitochondrial autophagy through Sirt1 pathway, which may be a potential mechanism for GpS to reduce the level of autoantibodies, kidney inflammation, immune complex deposition and urinary protein excretion, improve kidney function in lupus-prone mice." (PMID 36700474, 2022). "RT–PCR and Western blotting were used to detect the protein and mRNA expression levels of SIRT1, FoxO1, and MDR1 in SR splenic lymphocytes from lupus mice (SLCs/MPs)." (PMID 35022006, 2022). "The SIRT1/FoxO1/MDR1 signalling pathway has been confirmed in drug resistance of tumour cells, but there is little research on the field of SR in lupus." (PMID 35022006, 2022). "Later studies in lupus CD4+ T cells demonstrated that ultraviolet B strongly activates AhR, which subsequently contributes to the low expression of SIRT1 by binding to the SIRT1 promoter." (PMID 33981300, 2021). "In lupus-prone MRL/lpr mice, a histone deacetylation gene, sirtuin-1 (Sirt-1), was found overexpressed, indicating a compensatory repression of gene over-reactivation." (PMID 31635056, 2019). "The present study suggested that PNS reversed P-gp-mediated SR via the SIRT1/FoxO1/MDR1 signalling pathway, which might become a valuable drug for the treatment of SR in lupus." (PMID 35022006, 2022). "No study to our knowledge has thus far addressed a role of SIRT1 in B cells, though SIRT1-knockout mice spontaneously exhibit a lupus-like phenotype." (PMID 25136908, 2014). "To further investigate the mechanism of SIRT1 and ESR1 involvement in lupus pathogenesis, we analyzed SIRT1 and ESR1 using GSEA and also found that SIRT1 and ESR1 were involved in many biological processes of immune cells, which had been demonstrated in SLE." (PMID 38835801, 2024).